CFTR (CF transmembrane conductance regulator)
Diseases named in the same sentence as CFTR in open-access papers (continued):
Sharing a sentence is not in itself a finding about the gene and the disease.
cystic fibrosis (continued). "To further assess the functional efficacy of H7, we sought to correct PTCs in primary cells from cystic fibrosis patients harboring a nonsense mutation in the cystic fibrosis transmembrane conductance regulator gene (CFTR)." (PMID 29131862, 2017). "TMA was found to be potentially useful in the treatment of cystic fibrosis, thanks to its anti-inflammatory activity and its potentiating action on the CFTR membrane channel whose dysfunction causes that disease." (PMID 29089668, 2017). "Cystic fibrosis is the most prevalent autosomal recessive disorder in the Caucasian population and is caused by mutations in the cystic fibrosis transmembrane conductance regulator (CFTR) gene." (PMID 28069067, 2017). "There are >1985 recognized mutations in the CF transmembrane conductance regulator (CFTR) gene (Cystic Fibrosis Mutation Database: The Hospital for Sick Children, Genetics and Genomics Biology." (PMID 28981651, 2017). "Pulmonary disease is the major cause of morbidity and mortality in patients with cystic fibrosis, a disease caused by mutations in the Cystic Fibrosis Transmembrane conductance Regulator (CFTR) gene." (PMID 28649446, 2017). "More than 1950 CFTR variants have been identified in different ethnic populations, as curated in the cystic fibrosis genetic analysis consortium database." (PMID 28042420, 2017). "Cystic fibrosis, caused by mutations in the CF transmembrane conductance regulator gene, is a common autosomal recessive disease." (PMID 29399219, 2017). "Homozygous SLC26A3 mutations cause congenital chloride diarrhea with male subfertility, while homozygous CFTR mutations cause cystic fibrosis with male infertility." (PMID 29079751, 2017). "Cystic Fibrosis is an autosomal recessive disorder caused by mutations in the CF transmembrane conductance regulator (CFTR) gene, which encodes a transmembrane anion channel transporting chloride and bicarbonate." (PMID 29299029, 2017). "The ABCC subfamily includes 12 genes, including ABCC6 and ABCC7 (the latter also being known as CFTR – the mutated gene in cystic fibrosis), and a pseudogene (ABCC13)." (PMID 28486967, 2017). "Dysfunction of CFTR causes cystic fibrosis, the most common lethal autosomal recessive disease in Caucasians27." (PMID 28701694, 2017). "Gene mutations in CFTR cause cystic fibrosis, the most common autosomal-recessive disorder in Caucasians, with a disease incidence of around 1 in 1000–3000 in northern Europeans1." (PMID 28615646, 2017). "These patients were selected from the French National Cystic Fibrosis Register as having a nonsense mutation on both CFTR alleles." (PMID 29131862, 2017). "Cystic fibrosis is a multisystemic disease caused by a mutation in the gene that codifies for the CF transmembrane conductance regulator (CFTR), a chloride channel located in the apical membrane of epithelial cells from several tissues." (PMID 29246256, 2017). "A good example is the use of exome sequencing to identify a rare genetic modifier of clinical outcome in cystic fibrosis, which is commonly caused by variants in the cystic fibrosis transmembrane conductance regulator (CFTR)." (PMID 28686619, 2017). "Cystic fibrosis is an autosomal recessive disorder due to mutations in CFTR gene leading to abnormality of chloride channels in mucus and sweat producing cells." (PMID 28449677, 2017). "The CFTR gene is highly associated with cystic fibrosis, which often has CRSwNP as one of its clinical features." (PMID 29253858, 2017). "Mutations of CFTR result in cystic fibrosis, a lethal genetic disease with multi-organ defects, including infertility." (PMID 28978008, 2017). "Cystic fibrosis is an autosomal recessive disorder which impacts the protein encoded by the cystic fibrosis transmembrane conductance regulator (CFTR) gene." (PMID 29124055, 2017).
cystic fibrosis (continued). "Cystic fibrosis is the most common life-shortening genetic disease in the Caucasian population, caused by a mutation in the cystic fibrosis transmembrane conductance regulator (CFTR) gene." (PMID 27049850, 2016). "Cystic fibrosis is a life-shortening autosomal recessive disease caused by mutations in the gene that encodes the CFTR, a protein with anion-channeling properties that participates in electrolyte homeostasis and fluid movement across mucosal surfaces." (PMID 26861387, 2016). "Defective CFTR activity causes cystic fibrosis, a disease characterized by an impaired Cl- secretion and unbalanced Na+∕Cl-transport that leads to airway surface liquid (ASL) volume depletion and defective mucociliary clearance." (PMID 27092946, 2016). "Of particular importance is the cAMP-dependent cystic fibrosis transmembrane conductance regulator Cl- channel (CFTR) with mutations of the CFTR encoding gene causing cystic fibrosis." (PMID 27092946, 2016). "Cystic fibrosis is a genetic disorder in Caucasians caused by mutations in the CF transmembrane conductance regulator (CFTR) gene." (PMID 27735846, 2016). "W1282X is a common nonsense mutation among cystic fibrosis patients that results in the production of a truncated Cystic Fibrosis Transmembrane Conductance Regulator (CFTR) channel." (PMID 27007499, 2016). "The importance of epithelial ion transport is highlighted by the disease cystic fibrosis, a monogenic disorder resulting from mutations in the cystic fibrosis transmembrane conductance regulator (CFTR, ABCC7)." (PMID 26950439, 2016). "Two patients had sickle cell trait, two had β-thalassemia trait, one had CFTR gene mutation (cystic fibrosis heterozygosity), and four females had G6PD gene mutations (glucose-6-phosphatase dehydrogenase heterozygosity)." (PMID 27391121, 2016). "Mutations in the cystic fibrosis transmembrane conductance regulator (CFTR) gene cause cystic fibrosis – the most common life-limiting autosomal recessive inherited disorder in Caucasian people." (PMID 27656143, 2016). "Cystic fibrosis is a genetic disease caused by the mutation of Cystic fibrosis transmembrane conductance regulator (CFTR)." (PMID 27483469, 2016). "Cystic fibrosis is a systemic disorder caused by genetic mutations in the cystic fibrosis transmembrane conductance regulator (CFTR) channel that results in dysfunctional chloride ion transport." (PMID 27754353, 2016). "Cystic fibrosis, caused by mutations in cystic fibrosis transmembrane conductance regulator (CFTR), is characterized by multiorgan pathology, mainly affecting the upper and lower airways, gastrointestinal tract, and endocrine system." (PMID 27168400, 2016). "Cystic fibrosis is a fatal hereditary disorder resulting from mutations in the CF transmembrane conductance regulator (CFTR) anion channel." (PMID 27574522, 2016). "In CFTR, the chloride channel mutated in cystic fibrosis patients, ATP-binding-induced dimerization of two cytosolic nucleotide binding domains (NBDs) opens the pore, and dimer disruption following ATP hydrolysis closes it." (PMID 27328319, 2016). "Lung disease determines the morbidity and mortality of patients with cystic fibrosis, a lethal monogenetic disease caused by mutations in the cystic fibrosis transmembrane conductance regulator (CFTR) gene." (PMID 26905568, 2016). "Cystic fibrosis, the most common lethal hereditary disease in the Caucasian population, is caused by mutations in CFTR that lead to impaired anion conductance at the apical membrane of secretory epithelia." (PMID 27382190, 2016). "Cystic fibrosis results from mutations in the cystic fibrosis transmembrane conductance regulator (CFTR), a cAMP-dependent protein kinase A (PKA) and ATP-regulated chloride channel." (PMID 26950439, 2016).
cystic fibrosis (continued). "Orkambi (Vertex Pharmaceuticals), the first FDA-approved drug for treatment of cystic fibrosis caused by this mutation, is a combination of a corrector (VX-809) that facilitates ΔF508 CFTR biogenesis and a potentiator (VX-770), which improves its function." (PMID 27214033, 2016). "Conversely, aquagenic keratoderma has also been suggested to be associated with mutations in the CFTR gene involved in cystic fibrosis." (PMID 27255181, 2016). "CFTR encodes an ATP-binding cassette membrane protein that functions as a chloride channel and is mutated in cystic fibrosis, the most common autosomal recessive disorder among people of European ancestry." (PMID 27527254, 2016). "Cystic fibrosis is a genetic disease due to mutations in the cystic fibrosis transmembrane regulator (CFTR), F508del-CFTR being the most frequent." (PMID 27626054, 2016). "The situation is reminiscent of observations on the epithelial CFTR Cl− channel mutated in cystic fibrosis." (PMID 27445835, 2016). "Cystic fibrosis is a disease associated with mutation in the gene for cystic fibrosis transmembrane conductance regulator (CFTR) and can affect many organs." (PMID 27827953, 2016). "Several recessive Mendelian disorders are common in Europeans, including cystic fibrosis (CFTR), medium-chain-acyl-Co-A-dehydrogenase deficiency (ACADM), phenylketonuria (PAH) and alpha 1-antitrypsin deficiency (SERPINA1)." (PMID 26831755, 2016). "Mutations in the CFTR gene cause Cystic Fibrosis, the most common autosomal recessive disorder among Caucasians." (PMID 26835446, 2016). "Cystic fibrosis is caused by loss-of-function mutations in an epithelial anion channel, the cystic fibrosis conductance regulator (CFTR)." (PMID 27007499, 2016). "A phase II prospective clinical trial of ataluren was performed in adult patients with cystic fibrosis and a class I CFTR mutation; the trial included 23 participants in the first cycle and 21 in the second." (PMID 26403534, 2015). "The use of ivacaftor, a potentiator of CFTR function, has become a successful reality since 2012 as a targeted therapy for patients with cystic fibrosis caused by specific genotypes, and represents a powerful example of precision medicine." (PMID 26403534, 2015). "Mutations on both alleles of the Cystic Fibrosis Transmembrane Conductance Regulator (CFTR) are the genetic cause of Cystic Fibrosis, the most common single-gene caused disease in Caucasians." (PMID 25742660, 2015). "Lung delivery of plasmid DNA encoding the CFTR gene complexed with a cationic liposome is a potential treatment option for patients with cystic fibrosis." (PMID 26149841, 2015). "Over 1000 different mutations in the CFTR gene have been associated with cystic fibrosis, but some mutations are more common than others and there are ethnic and regional preponderances." (PMID 28031875, 2015). "Cystic fibrosis is caused by mutations of the gene encoding the cystic fibrosis transmembrane conductance regulator (CFTR), a membrane protein functioning as a chloride channel and expressed at the surface of many epithelia." (PMID 26485688, 2015). "The identification of small molecules that target specific CFTR variants has ushered in a new era of treatment for cystic fibrosis, yet optimal, individualized treatment of CF will require identification and targeting of disease modifiers." (PMID 26417704, 2015). "The genetic disorder cystic fibrosis results from a loss of function variant in the cystic fibrosis transmembrane conductance regulator (CFTR) gene." (PMID 26097506, 2015). "Cystic fibrosis imposes a decline in quality of life but new treatments are being developed that target specific CFTR variants." (PMID 26417704, 2015). "F508del-CFTR, or delta-F508 (ΔF508), is the most common CFTR mutation leading to cystic fibrosis F508del-CFTR is a class II mutation." (PMID 28031875, 2015).
cystic fibrosis (continued). "People who are homozygous for class I, II and III mutations most often have a severe cystic fibrosis phenotype and some examples of these classes of CFTR mutation are explored here in more detail." (PMID 28031875, 2015). "4-PBA is a chemical chaperone drug that has already been successfully used in cystic fibrosis to restore the plasma membrane localization of CFTR (cystic fibrosis transmembrane conductance regulator, OMIM∗602421) in the presence of the frequent Δ508 mutation." (PMID 26356190, 2015). "Cystic fibrosis is a disease caused by mutations in the gene coding for cystic fibrosis transmembrane conductance regulator (CFTR), an anion channel expressed in epithelial surfaces." (PMID 26793709, 2015). "Cystic fibrosis is the result of mutations in the CF transmembrane conductance regulator affecting epithelial chloride and bicarbonate transport." (PMID 26252384, 2015). "The absence or dysfunction of the fibrosis regulator protein (CFTR) is thought to be key in the pathogenetic sequence of cystic fibrosis associated liver disease." (PMID 26609528, 2015). "This discovery has clinical ramifications for the treatment of disease states associated with enhanced S1P signaling and/or deficient CFTR activity (e.g. cystic fibrosis, heart failure)." (PMID 26079370, 2015). "Ivacaftor acts as a potentiator of the cystic fibrosis transmembrane conductance regulator (CFTR) and increases the transepithelial chloride transport of CFTR in 9 of 10 known gating mutations causing cystic fibrosis." (PMID 26474553, 2015). "Cystic Fibrosis is caused by mutations in the chloride channel CFTR gene which secondarily increases sodium reabsorption in the airways." (PMID 25626868, 2015). "An exception, however, is cystic fibrosis, in which the underlying genetic defect is well defined and lies within the CFTR gene." (PMID 26403534, 2015). "In November 2014, Vertex submitted the combination of lumacaftor and ivacaftor for cystic fibrosis patients aged 12 years and older with two copies of the F508del mutation in the CFTR gene for registration both in the U.S. and in the EU." (PMID 27417354, 2015). "As it is a key Cl− channel for regulating epithelial ion and fluid transport, the loss of CFTR (OMIM-602421) underlies cystic fibrosis, a recessive disease characterized by mucus build-up in several organs." (PMID 26432887, 2015). "The KONNECTION study was a two-part randomized international multicenter study designed to investigate the safety and efficacy of ivacaftor in patients with cystic fibrosis over the age of 6 years with a non-Gly551Asp CFTR gating mutation." (PMID 26403534, 2015). "Cystic fibrosis, which is caused by mutation in CF transmembrane conductance regulator (CFTR), affects about 30,000 people in the US." (PMID 26509529, 2015). "The identification of small molecules that target specific CFTR variants has ushered in a new era of treatment for cystic fibrosis 2, but optimal individualized treatment will require identification and targeting of disease modifiers." (PMID 26417704, 2015). "Ataluren is an orally bioavailable agent that has been trialed for use in class I CFTR mutations, which affect around 10 % of patients with cystic fibrosis." (PMID 26403534, 2015). "Ivacaftor acts as a potentiator of the cystic fibrosis transmembrane conductance regulator (CFTR) and increases the transepithelial chloride (Cl−) transport of CFTR in 9 of 10 known gating mutations and in R117H mutation (class IV) causing cystic fibrosis." (PMID 26474553, 2015). "Cystic fibrosis is a multifactorial disease caused by mutations in the cystic fibrosis transmembrane conductance regulator gene (CFTR), which encodes a cAMP-dependent Cl- channel." (PMID 26594334, 2015). "A wide variety of mutations in CFTR have been characterized which have been linked with the cystic fibrosis phenotype." (PMID 28031875, 2015).
cystic fibrosis (continued). "In comparison, cystic fibrosis is caused by mutations in CFTR, resulting in abnormal mucus and impaired lung function." (PMID 26480348, 2015). "Cystic fibrosis is a multifaceted autosomal recessive disease caused by mutations in the CF transmembrane conductance regulator (CFTR) gene." (PMID 26185362, 2015). "Another study of ataluren was performed in children and young people with cystic fibrosis aged between 6 and 18 years with a class I CFTR mutation." (PMID 26403534, 2015). "Variants in the CFTR gene are known to cause cystic fibrosis, often comorbid with iodine deficiency and subclinical hypothyroidism, thereby indicating a potential functional link to our phenotype of interest." (PMID 26261983, 2015). "The Phe508del CFTR mutation is much more common and is present in around 85 % of people with cystic fibrosis." (PMID 26403534, 2015). "Cystic fibrosis is an autosomal recessive disorder caused by mutations in a single gene coding for the CF transmembrane conductance regulator (CFTR) protein." (PMID 25602268, 2015). "A heritable change in the CFTR gene which results in a single amino acid deletion in the protein causes cystic fibrosis." (PMID 26504250, 2015). "Cystic fibrosis is a recessive genetic disease, caused by a mutation in the cystic fibrosis transmembrane conductance regulator (CFTR) gene, affecting many organ systems throughout the body." (PMID 26047144, 2015). "Genetic testing for cystic fibrosis and CFTR-related disorders mostly relies on laborious molecular tools that use Sanger sequencing to scan for mutations in the CFTR gene." (PMID 26436105, 2015). "During cystic fibrosis, the loss of functional CFTR leads to a disruption in the regulation of ion channels at the cell membrane, namely, the negative regulation of sodium absorption through the apically located sodium channel, ENaC." (PMID 25626868, 2015). "This culture system can be applied to hFSCs carrying the CFTR mutation Δf508, enabling the development of an in vitro model for cystic fibrosis." (PMID 25758640, 2015). "Recently, calumenin was found to interact with the G551D cystic fibrosis transmembrane conductance regulator (CFTR) protein that is causing cystic fibrosis." (PMID 26161649, 2015). "Cystic fibrosis is caused by mutations in the cystic fibrosis transmembrane conductance regulator (CFTR) gene that codes for a chloride channel that mediates proper movement of chloride ions in epithelial cells." (PMID 25753687, 2015). "The genetic basis of cystic fibrosis is well established to be mutations in the cystic fibrosis transmembrane conductance regulator (CFTR) gene that codes for an apical membrane chloride channel principally expressed by epithelial cells." (PMID 26403534, 2015). "The deletion of Phe-508 in CFTR is responsible for the majority of cystic fibrosis cases and causes CFTR misfolding and retention in the endoplasmic reticulum, as well as defective channel function." (PMID 26229102, 2015). "Cystic Fibrosis is a frequent and lethal autosomal recessive disease caused by mutations in the gene encoding the Cystic Fibrosis Transmembrane Conductance Regulator (CFTR)." (PMID 26709821, 2015). "The CFTR chloride channel is encoded by the ABCC7 gene, which is mutated in patients with cystic fibrosis." (PMID 25769815, 2015). "Cystic fibrosis, also hallmarked with pulmonary inflammation, is caused by mutations in CFTR, the expression of which is temperature-sensitive." (PMID 26515683, 2015). "Cystic Fibrosis, a complex disease associated with widespread exocrine gland dysfunction, is caused by loss of function of the CF transmembrane conductance regulator (CFTR) chloride channel." (PMID 26092868, 2015). "Mutations of the cystic fibrosis transmembrane conductance regulator (CFTR) gene cause the autosomal recessive inherited disease of cystic fibrosis." (PMID 26770278, 2015).